PAF1 (PAF1 component of Paf1/RNA polymerase II complex)
Diseases named in the same sentence as PAF1 in open-access papers (continued):
Sharing a sentence is not in itself a finding about the gene and the disease.
cancer (32 papers, 2011 to 2025). A tumor composed of atypical neoplastic, often pleomorphic cells that invade other tissues. "RNA polymerase II-associated factor 1 (PAF1) maintains cancer stem cells leading to the aggressiveness of PDAC." (PMID 36180487, 2022). "In the years following its discovery, PAF1 has been found to be highly expressed in various cancers and is associated with tumor metastasis, diminished differentiation, therapeutic sensitivity, and poor prognosis." (PMID 32471508, 2020). "Cancer-associated BRCA2 mutations diminish PAF1 recruitment to the polymerase, provoking unscheduled R-loop accumulation at promoter-proximal pause sites and triggering DNA breakage." (PMID 29386125, 2018). "The human PAF1 complex is linked to cancer, and in yeast, it has been reported to play a role in telomere biology." (PMID 29564528, 2018). "Loss of PINT87aa makes PAF1 lose its proper position, and the freed PAF1 is sequentially involved in many other biological processes such as cell cycle regulation, histone modification, and self-renewal of cancer stem cells." (PMID 35223470, 2022). "Notably, cancer-associated truncating mutations that delete a C-terminal region of the BRCA2 protein retain RNAPII interaction but nevertheless diminish PAF1 recruitment to increase RNAPII accumulation and R-loop accrual at PPP sites." (PMID 29386125, 2018). "Finally, human CDC73 and CTR9 genes are frequently found mutated in cancer, and are the only PAF1 complex genes to be currently classified as tumour suppressors." (PMID 29145644, 2018). "Lack of tractable enzymatic activities limits the potential of PAF1 or other subunits of the PAFc as therapeutic targets in cancer." (PMID 34083515, 2021). "PAF1 is known to have context-dependent impacts on transcription elongation in cancer cell lines but appears to exclusively promote transcriptional elongation in primary mammalian cells." (PMID 34797876, 2021). "It seems plausible that one of the ways that the PAF1 complex affects human cancer is by affecting TERRA." (PMID 29145644, 2018). "Loss of PINT87aa or overexpression of PAF1, which was seen in many cancers, results in PAF1 losing its proper localization." (PMID 30367041, 2018). "In contrast, recent work in cancer cells and flies showed that depletion of Paf1 led to dramatic enhancement of CDK9 recruitment, coincident with release of paused PolII and increased phosphorylation of Ser2 on the CTD." (PMID 26765774, 2016). "Mechanistically, A-PaschiRNA induces cancer stemness by activating extracellular-signal-regulated kinase 5 (ERK5)-mediated non-canonical RNA Polymerase II-Associated Factor 1 Homolog (PAF1)." (PMID 35053393, 2022). "CA3, an inhibitor of YAP/TEAD transcriptional activity, inhibits the proliferation and metastasis of other cancers; however, whether it inhibits PAF1-mediated YAP1/TEAD4 transcriptional activity and cancer stem cells in PC is unknown." (PMID 36180487, 2022). "Overall, these studies validated the positioning of PAF1 at the crossroads of the cancer network." (PMID 32471508, 2020). "However, aberrant overexpression of SETD5 may cause reactivation of stem cell marker genes via PAF1-mediated recruitment of RNA Pol II at their TSS, contributing to the stem cell-like phenotypes of cancer cells." (PMID 37963940, 2023). "However, little is known about how CDC73 and CTR9 function as tumor suppressors, particularly since mutations in the genes encoding the other members of the Paf1 complex have not yet been linked to the development of cancer." (PMID 29320491, 2018). "Our findings suggest that CDX1/2 cooperatively suppressed colonic tumorigenesis and cancer stemness by antagonizing β-catenin via the DSIF and PAF1 complexes." (PMID 40399276, 2025). "In a similar manner to the PAF1 knockdown, CDC73 or CTR9 knockdown inhibited cell proliferation, reduced the expression levels of most cancer stem cell marker genes including LGR5 and ID1, and increased those of KRT20 and MUCs." (PMID 38182897, 2024).
cancer (continued). "For instance, PHF1 engages with PRMT5–WDR77 and CRL4B complexes to promote cancer progression, while PHF5A’s interaction with the SF3b spliceosome and PAF1 impacts apoptotic pathways and cellular behavior across various cancers." (PMID 38813086, 2024). "CA3 treatment (1 μM; 48 h) in PC cells reduced the protein expression levels of PAF1, YAP1, TEAD4, CD133 (cancer stem cell marker), and SOX9 (pancreatic ductal marker)." (PMID 36180487, 2022). "Although its role in cancer is still unclear, recent studies reported that PPIF up-regulation seems to play a role in the tumor progression, through the Paf1/MEK/ERK pathway." (PMID 28686225, 2017). "Previously, we demonstrated that A-PaschiRNA can induce cancer stemness by activating ERK5-mediated non-canonical PAF1." (PMID 35053393, 2022). "For instance, while MITF, SPDEF, CNOT7, BTK, PAF1, and PAX5 seem to be novel key regulators in the context of HPV-induced carcinogenesis, they are apparently already known to play essential roles in other cancer entities." (PMID 30918060, 2019).
tumor (28 papers, 2009 to 2025). "In turn, it is the PINT87aa ncPEP to be endowed with a tumor-suppressive role: in the nucleus, it directly interacts with RNA Polymerase II-Associated factor 1 (PAF1) and inhibits the elongation of the primary transcript of several oncogenes." (PMID 39054345, 2024). "Studies in recent years have suggested that Pol II-associated factor 1 (PAF1) is a pivotal transcription factor for certain genes “induced” during tumor progression." (PMID 32471508, 2020). "The tumor suppressor Hyx is a component of the Polymerase-Associated Factor 1 (PAF1) complex and has recently been found to be required for nuclear transduction of the Wnt/Wg signal in Drosophila." (PMID 19885390, 2009). "Continuous knockdown of PAF1 reduced tumor weight and size to less than 20%, which was a stronger effect than that observed for continuous knockdown of CTNNB1." (PMID 38182897, 2024). "Recent studies have reported that PAF1 is an oncogene and is closely related to tumor differentiation, metastasis, therapeutic resistance, and prognosis." (PMID 32471508, 2020). "Specifically, the inflammatory insult led to downregulation (which subsequently restored) of acinar PD2/Paf1 expression in normal mice, but in KC mice, it continued to be ablated with progressive neoplasia." (PMID 24947474, 2014). "Here we have investigated how the Paf1 complex acts to suppress genome instability with the goal of shedding light on how the human homolog of CDC73 may function as a tumor suppressor." (PMID 29320491, 2018). "These analyses enhance our understanding of how Cdc73, as a subunit of the Paf1 complex, suppresses genome instability, and provide insights into how its human homolog may function as a tumor suppressor." (PMID 29320491, 2018). "Overall, these studies strongly suggest a concerted function between Paf1 and CHD1 proteins in regulating gene expression, thereby affecting the process of cell cycle progression, differentiation or tumor development." (PMID 22046413, 2011). "The analysis revealed that in the training set, the expression of BANF1, CDK2AP2, DDT, LRIG1, MRPL4, and S100A13 was significantly upregulated in tumor samples, and the expression of EPS8, NUCB2, PAF1, PMP22, RABGAP1L, and USO1 was higher in control samples (p < 0.05)." (PMID 41000388, 2025). "Interestingly, PAF1 and YAP1 were co-localized and co-expressed in metaplastic ducts and PDAC tumor tissues." (PMID 36180487, 2022). "Although PAF1 is a subunit of PAF1C, it functions independently in the process of carcinogenic transformation (mostly independently of the other subunits), including tumor cell cycle alterations, chromatin composition changes, tumor cell renewal and tumor stem cell pluripotency." (PMID 32471508, 2020).
infection (11 papers, 2011 to 2025). The state of being infected such as from the introduction of a foreign agent such as serum, vaccine, antigenic substance or organism. "This replication advantage in PAF1 KO cells was significant (p ≤ 0.05) but disappeared at 96 hours post-infection." (PMID 34797876, 2021). "Infectious virion production increased approximately 3-fold at 48- and 72-hours post-infection in PAF1 KO cells." (PMID 34797876, 2021). "Given the strong nuclear localization of NS5 during infection, we tested if this nuclear localization is required for its interaction with PAF1." (PMID 34797876, 2021). "We found that PAF1 colocalized with ICP4 at both infection stages, implicating PAF1 with both parental and progeny HSV-1 genomes." (PMID 31337724, 2019). "A striking observation is that enhancement of infection results after independent knockdown of 3 components of the PAF1 complex (PAF1c), PAF1, CTR9 and RTF1 (A3, Z scores from the initial screen of 4.4, 3.3 and 8.5 respectively)." (PMID 22082156, 2011). "Furthermore, infection by IAV mutants unable to antagonize PAF1 resulted in stronger ISG expression, and these IAV mutants had improved replication in PAF1-depleted cells." (PMID 37243120, 2023). "Hence, PAF1 could be required for maintaining a proviral microenvironment for some viruses, but perhaps this only occurs when certain immune pathways are activated during infection." (PMID 36451099, 2022). "Infectious virion production was approximately 5- and 14-fold higher at 72 and 96 hours post-infection, respectively in GFP-expressing PAF1 KO cells compared to PAF1 rescue cells." (PMID 34797876, 2021). "To explore this, we assessed the colocalization of PAF1 and ICP4 at early stages of infection (1 and 6 hpi), when we and others previously observed HSV-1 genome deposition into the nucleus and the presence of viral replication compartments." (PMID 31337724, 2019). "In addition, we found productive infection to upregulate IFI16 and PAF1 in myeloid cells." (PMID 39798087, 2025).
PAF1 also shares sentences with these, for which no sentence is quoted: Parkinson disease (5 papers); neurodegenerative disease (3); chronic periodontitis (2); COVID-19 (2); dengue (2); glioma (2); lung carcinoma (2); periodontal disease (2); acute leukemia (1); acute pancreatitis (1); cervical cancer (1); cholangiocarcinoma (1); CNS tumors (1); colorectal adenocarcinoma (1); colorectal cancer (1); diabetes (1); Gaucher disease (1); hepatoma (1); hyperparathyroidism (1); Insulin resistance (1); liver cancer (1); metastatic tumors (1); non-small cell lung carcinoma (1); Obesity (1); parathyroid carcinomas (1); peritonitis (1); renal cell cancer (1); rhabdomyosarcoma (1); Sepsis (1); sleep disorder (1).
A further 3 diseases each share a sentence with PAF1 in 1 paper.